IRF1 (interferon regulatory factor 1)
Diseases named in the same sentence as IRF1 in open-access papers (continued):
Sharing a sentence is not in itself a finding about the gene and the disease.
infection (continued). "While the protective IRF1 polymorphisms restrict HIV replication during the early stages of infection, their impact on disease progression remains unknown." (PMID 23799084, 2013). "It seems likely that at low activation levels in the mucosal tissues the effect of reduced IRF1 expression due to genetic polymorphisms may be sufficient to prevent initial viral replication and establishment of infection." (PMID 23799084, 2013). "Again, similar levels of cell death and IL-18 release were observed in WT and IRF1-deficient BMDMs in response to infection with E. coli and C. rodentium, whereas BMDMs deficient in caspase-11 had no cell death and impaired IL-18 release in response to these infections." (PMID 37557956, 2023). "To further verify these results, we generated mice with conditional Irf1-deficiency in the hematopoietic and endothelial (Irf1ΔTie2) and in the intestinal epithelial (Irf1ΔIEC) compartments and compared the systemic spread of C. rodentium after infection in these mice." (PMID 36175404, 2022). "Among the genes positively regulated by IRF1 signalling and directly bound by IRF1, we found the already known targets, guanylate-binding protein 2 (Gbp2) and Gbp5 (refs 50, 51), which contribute to clearance of infection as well as Th1-associated genes, including Il12rb1 (refs 1, 36)." (PMID 28497800, 2017). "In conclusion, M1‐and M2‐like signals synergistically regulate Calhm6 expression via Irf1 and Stat6, maintaining a balance between anti‐infection and immune tolerance signals in vivo and preventing macrophages from overly differentiating to either phenotype." (PMID 40999918, 2026). "Upon infection with ALV-J, there was a notable upregulation in the expressions of GATA1 and IRF1 within 24 h, followed by a subsequent decrease at 36 h post-infection (hpi)." (PMID 40075948, 2025). "IRF1 functions within a complex regulatory network, exhibiting context-dependent roles as both a pro-survival mediator in early infection and a pro-apoptotic agent in chronic inflammation." (PMID 40420582, 2025). "Our analysis reveals that at 4 h post-MVA infection, IRF1 expression is specifically upregulated in DSK cells, whereas no such upregulation is observed in WT DF-1 cells." (PMID 40981440, 2025). "Mechanistically, IRF1 can rapidly and dynamically respond to infections and suppress viral replication." (PMID 40420582, 2025). "Constitutive levels of IRF-1, ISGs, and other immune factors are detected in H820 cells, and their expression levels are further increased upon infection." (PMID 40434103, 2025). "Basal expression of IRF1 sets up an antiviral state in cells, preparing them to respond rapidly to infections." (PMID 40586041, 2025). "Given the observed antiviral phenotype of global IRF-1 expression during chronic MHV68 infection, we generated a mouse model of B cell-intrinsic IRF-1 deficiency by combining conditional IRF-1 alleles with CD19 promoter-driven Cre recombinase knock-in allele." (PMID 41263556, 2025). "The prolonged pro‐inflammatory and infection‐prone environment of DFU undoubtedly leads to increased IRF1 expression." (PMID 39730319, 2024). "Given the correlation of IRF-1 expression and the response in glucose/IFN-γ, we next considered the role of IRF1 in contributing to the differences in infection outcomes associated with glucose/galactose." (PMID 39475961, 2024). "Interferon regulatory factor 1 (IRF1) plays an essential role as a transcription factor in driving the expression of immune response genes during infection." (PMID 37622993, 2023). "Next, we evaluated the role of IRF1 in mediating cell death in response to infection with E. coli and Citrobacter rodentium, which activate the noncanonical NLRP3 inflammasome through caspase-11 activation." (PMID 37557956, 2023). "Infection of both viruses efficiently induced ISGs and activated IRF1, IRF3 and IRF7, suggesting that the antiviral innate response of infected cells is not fully suppressed during infection." (PMID 37197656, 2023).
infection (continued). "When these cells were challenged with 229E or OC43, RT-q-PCR analysis revealed that IRF1 knockdown promotes 229E infection at 3 days after infection and OC43 infection at 2 and 3 days after infection." (PMID 37197656, 2023). "EV71 is a highly infectious RNA virus that induces type III interferon (IFN-γ) production after infection by stimulating the toll-like receptor 3/interferon regulatory factor 1 (TLR3/IRF1) signaling pathway." (PMID 37649892, 2023). "As the earliest discovered interferon regulator, IRF1 is activated by stimuli such as infection or DNA damage and incorporated into the nucleus, thereby initiating the transcription of interferon-related genes." (PMID 38203518, 2023). "As expected, infection of DF1 cells with a recombinant overexpression lentivirus was effective in driving IRF1 expression (OE-IRF1), whereas infection with a knockdown lentivirus (shRNA1-3) had the opposite effect." (PMID 36882743, 2023). "Together, these data suggest that IRF1 is dispensable for inflammasome activation and cell death in response to infection with both NLRC4 inflammasome–activating pathogens as well as caspase-11–activating pathogens." (PMID 37557956, 2023). "When interrogating the Vis AD cell proteome for proteins involved in the “interferon signaling” pathway, we found seven proteins altered by infection with CoV-2(P.1), among which five were upregulated (i.e., IRF1, HLA-C, TPR, EIF4G1, and TRIM28)." (PMID 36175400, 2022). "The transcriptional changes upon infection were dominated by Ifng and its downstream genes (e.g. Stat1, Irf1, Fcgr1, Nos2, Cxcr3) and IFN-dependent CXCR3 binding chemokines (e.g. Cxcl9, Cxcl10)." (PMID 36400767, 2022). "We demonstrate that IRF-1 is upregulated in the context of infection with the enteropathogen Citrobacter rodentium and that its presence is central for anatomical containment and prevention of pathogen dissemination." (PMID 36175404, 2022). "It has been well-characterized that IRF1 is involved in the immune response to viral and bacterial pathogen infection." (PMID 36498991, 2022). "In RAW264.7 cells, IRF1 expression decreased after co-inoculation of OMV+MNV compared to infection with MNV alone for both types of OMVs as well as both OMV concentrations tested." (PMID 35990695, 2022). "In contrast to poly(I:C) transfection, IRF1 expression during infection actually increased over time in the KD/KO cells compared to WT cells." (PMID 35085371, 2022). "C. rodentium detection by immunohistochemical staining clearly demonstrated colonization of deep colonic crypt spaces in untreated Irf1–/– mice compared to Irf1-proficient mice at day 7 post infection." (PMID 36175404, 2022). "We furthermore show that IRF-1 is required in order for intestinal ILC3s to produce large amounts of the protective effector cytokine IL-22 early in the course of infection." (PMID 36175404, 2022). "We investigated downstream targets of interferon signaling, including STAT1, STAT2, pSTAT1 and 2, and IRF1, 7 and 9 by flow cytometry in 30 patients with COVID‐19, 17 with mild, and 13 with severe infection." (PMID 34676541, 2022). "The absolute numbers of CCR6+NKp46- ILC3s were also reduced in Irf1–/– mice indicating that IRF-1 transcription controls cellularity of both ILC3 subsets during infection." (PMID 36175404, 2022). "Some interferon regulatory factors (irf1, irf3, irf4b, irf5, irf6, irf8) continued to show upregulation during the later stages of infection (day 6 to day 10) in virus-infected fish spleens." (PMID 36016951, 2022). "Collectively, these data indicate that Irf1-deficiency in the hematopoietic compartment is associated with a reduced capacity of intestinal lymphocytes to produce IL-22 and IFN-γ upon infection or IL-23 challenge." (PMID 36175404, 2022). "For instance, infection of African green monkey MA104 cells with homologous simian RRV also results in an early (12 hours post-infection) decrease in IRF1 protein levels." (PMID 35699371, 2022).
infection (continued). "Given that both the events of ASFV internalization and IRF1 activation occurs at early stage of ASFV infection, it is possible that IRF1 inhibits ASFV internalization." (PMID 36110293, 2022). "When performing an analysis focusing on inflammation and infection associated factors in IPA, we found a strong Z-score for IFNβ, IFNA2, IRF1, and IRF7 signaling." (PMID 36032117, 2022). "Cells were infected with a low multiple of infection (MOI) to establish a multicycle infection in Irf1 WT cells." (PMID 35852463, 2022). "Increases in IRF1 expression induced by infection primarily result from NF-κB and STAT1-mediated transcriptional activation." (PMID 33476326, 2021). "Taken together, ours and previously published data strongly suggest that both TBK1 and NF-κB are involved in IRF1 regulation upon infection with a wide set of viral species." (PMID 34248923, 2021). "After STM infection migratory ILCs express significantly higher levels of Ccl3, Gbp2, Gbp6, Irf1, Irf4, Irf7, Pml and Stat1, all of which are regulated in response to interferon gamma." (PMID 33414524, 2021). "At 96 hr, the total area infected per well was significantly lower for RARRES3 and IRF1 expressing cells compared to control as was the average size of infection foci." (PMID 34871166, 2021). "IRF1 controls the expression of multiple genes that are of fundamental importance to host protection against infection and restriction of not only viral, but also bacterial and fungal replication." (PMID 34248923, 2021). "Since RARRES3 was the only ISG identified by our screen to restrict T. gondii infection, we wanted to determine if the impact of IRF1 on infection was solely due to upregulation of RARRES3 expression." (PMID 34871166, 2021). "At later time-points of the infection, IRF1 expression depended heavily on IFN-β-mediated signaling via the IFNAR-STAT1 pathway." (PMID 34248923, 2021). "Most studies examining the role of IRF1 in pathogen defense suggest it is an inducible factor, triggered by infection and contributing to the activation of innate immune responses induced by pathogen sensors such as RLRs, TLRs, or cGAS." (PMID 33476326, 2021). "In this study we define a novel IRF1 regulatory link induced by infection with the airway pathogen HMPV." (PMID 34248923, 2021). "Protein expression levels of STAT1, pSTAT1, IRF-1, and pSTAT3 increased in WT mice during the course of infection." (PMID 33753412, 2021). "The concerted activities of these three functional domains determines the pathophysiologic impact of IRF1 during infection." (PMID 33476326, 2021). "Induction of IRF1 mRNA and protein were detectable as early as 1-3 hours post infection (h.p.i.)and increased markedly up to 18 h.p.i." (PMID 34248923, 2021). "IRF-1 is upregulated by infection of Measles virus (MeV, RNA virus) and contributes to the growth arrest of MeV-infected human epithelial cells and efficient virus proliferation through the modulation of host cell events." (PMID 34930359, 2021). "Upon infection, IRF1 is first activated by PRR signaling and then sustained via autocrine/paracrine TNF-α and IL-6." (PMID 34607464, 2021). "We next tested if IRF1 activation is involved in controlling M. avium infection by treating macrophages with small interfering RNA (siRNA) against IRF1 prior to infection with M. avium-DsRed for 3 days." (PMID 34607464, 2021). "Both IRF1 mRNA transcripts and the IRF1 protein itself are short-lived, allowing for rapid, dynamic regulation in response to infection." (PMID 33476326, 2021). "This suggests that either IRF1-mediated infection restriction is RARRES3 independent or involves multiple factors with RARRES3 playing a redundant role in the process of restricting growth." (PMID 34871166, 2021). "Fine-tuning of these ancient IRF1-mediated host defenses, and countering strategies by pathogens to disarm IRF1, play crucial roles in pathogenesis and determining the outcome of infection." (PMID 33476326, 2021).
infection (continued). "Irf1, Irf7, Irf8, and Irf9 transcripts were significantly induced by infection in Ifnar1-/- mice, whereas Irf6 transcripts (abundant in uninfected mice) were significantly down-regulated." (PMID 34591933, 2021). "The Irf1 and Stat1 contribute to the control of T. gondii by regulating the expression of factors essential for the host to resist infection, such as Socs1, Ciita, and NOS2." (PMID 33193165, 2020). "Further studies demonstrated that IRF1 activates IFN expression against infection through the MyD88-dependent signaling pathway." (PMID 32983049, 2020). "Collectively, the predominant induction of type III IFNs through activating the TLR3/IRF1 pathway is a common characteristic of IECs upon the infections with enteroviruses." (PMID 33203755, 2020). "We further proved that IRF1 can up-regulate VIPERIN gene expression during DTMUV infection, through induction of type 1 IFNs as well as directly binding to and activation of the VIPERIN promoter." (PMID 32983049, 2020). "Confirming the Irf1 transcription data, L. infantum-mCherry infection induced IRF1 expression in the WT BMDCs, whereas the Tlr4-/- BMDCs displayed significant reduction in protein expression (average of 50% reduction)." (PMID 32210480, 2020). "As expected, pre-infection of HFFs with TgRH88 tachyzoites or TgVEG sporozoites significantly suppressed IRF1 activation in response to IFNγ treatment (P<0.05), while prior infection with N. caninum tachyzoites did not." (PMID 32574210, 2020). "We found that infection with the wtCSFV strain or overexpression of Npro inhibited nuclear translocation of IRF1 in poly(I:C)-stimulated cells, while the ∆Npro mutant did not affect such translocation." (PMID 31683525, 2019). "Both AP-1 and NF-kB families of TFs, as well as Irf1, play important roles in macrophages and can be triggered by a range of infection response receptors including Toll-like and Nod-like receptors." (PMID 30669987, 2019). "Here we found that at day 9 post-HSV-1 flank infection, 5 of 6 examined IRF1 KO mice had gastrointestinal dysfunction; in some mice this even involved the stomach (red arrow)." (PMID 31619669, 2019). "We also analyzed interferon regulatory factor 1 (IRF-1) as a target gene of infection and a member of the interferon regulatory factor family." (PMID 31695702, 2019). "While infection of wild type and IRF1−/− keratinocytes resulted in higher ICP4 protein levels in the IRF1−/− cells in one experiment, this was not reproducible in other experiments." (PMID 31619669, 2019). "Both wtCSFV and ∆Npro infection induced time-dependent IRF1 expression in IPEC-J2 cells, with ΔNpro showing more significant induction, particularly at 24 hpi." (PMID 31683525, 2019). "Relative to infection with T3D-RV, T1L infection is associated with increased levels of inflammatory mediators, including type 1 IFNs and IFN regulatory factor-1 (IRF-1), which are up-regulated in the intestinal mucosa of CD patients." (PMID 30235320, 2018). "We monitored the activation of NF-kB (p65) and IRF-1 after infection of hLECs with Mtb WT, Mtb ΔPDIM and Mtb ΔPDIM∷PDIM by confocal microscopy as previously shown." (PMID 29325545, 2018). "Interferon regulatory factor-1 (IRF-1) has been shown to be necessary for the host defense against infection by M.tuberculosis in mice." (PMID 29386556, 2018). "As an important signalling transcriptional regulation factor, IRF1 plays a pivotal role in the activation of type I IFN responses during infections with viruses and bacteria and due to other responses." (PMID 30009167, 2018). "Additional pro-inflammatory markers in the NHP liver dataset included enriched Klf6, Stat1 and Irf1, as well as Il23 in late-stage infection." (PMID 29724035, 2018). "More importantly, infection of FCV can suppress the endogenous expression of fe-IRF1, suggesting a new strategy for FCV to evade the host antiviral response." (PMID 30009167, 2018).
infection (continued). "The low responders, Ghs6 and M15.2 (respectively), differ especially due to the downregulation of one or more of these genes, STAT1, CCL5, and IRF1, was predicted to increase viral replication and infection in the Ghs6 and M15.2 sublines." (PMID 29535762, 2018). "PFA-killed Mav induced nuclear translocation of IRF-1 and the response was sustained over the 3-day time course in comparison to infection with live Mav, where the percentage of Mav-infected cells with nuclear IRF-1 declined with time (P<0.005)." (PMID 28806745, 2017). "Nuclear translocation of IRF-1 was markedly reduced over the first 3 days of infection in macrophages treated with siRNA to MyD88, suggesting MyD88 is conveying Mav-induced responses from the LAMP1+ phagolysosome." (PMID 28806745, 2017). "In one of these models, the use of bioluminescent B. melitensis to infect intraperitoneally interferon regulatory factor-1 (IRF-1-/-) knockout mice enabled to identify acute infection in many tissues, even in the tail joint." (PMID 28265268, 2017). "Among the genes associated with responses to virus, TLR3, IRF1, GATA3, SAMHD1 and RSAD2 were all significantly up-regulated on both day 1 and day 3 post infection." (PMID 28486945, 2017). "NF-κB is one of the key transcription factors driving inflammatory responses, and we and others have demonstrated that IRF-1 is activated in various infections including mycobacteria." (PMID 28806745, 2017). "Interferon regulatory factor-2 (IRF-2) expression did not change in the bone marrow cells, whereas it decreased in spleen cells at 4 weeks and IRF-1 expression was up-regulated in both bone marrow and spleen cells after infection." (PMID 29259694, 2016). "and decreased by 4 and 12 weeks after infection, results that are similar to those for the IRF-1 expression in the spleen cells." (PMID 29259694, 2016). "Interferon regulatory factor, IRF-1, also was up-regulated at 2 weeks, reached a maximum expression level at 4 weeks, and was reduced by 12 weeks after infection, results that correlated with the expression of IFN-γ." (PMID 29259694, 2016). "In particular, during the early phase of infection, IRF-1 is induced by HIV-1 and, in combination with NF-κB, activates proviral transcription irrespective of the presence of Tat." (PMID 27795392, 2016). "In the context of EBOV GP/rVSV infection, delivery of IRF1 siRNA containing exosomes knocked down IRF1 mRNA levels by approximately 50% in both M-CSF- and M-CSF/IFNγ-treated macrophages." (PMID 26562011, 2015). "Increased numbers of infiltrating monocytes and activated microglia were detectable in IRF-1−/− mice compared to their WT counterparts 6 days post infection." (PMID 24675692, 2014). "Although type I IFN action is a prerequisite for survival from the infection, IRF-1 becomes increasingly crucial in neuronal tissue at a time point where clearance of the virus has not been achieved." (PMID 24675692, 2014). "Equal levels of IFN-α were detectable in the serum of both WT and IRF-1−/− mice at 6 hours and 24 hours post infection." (PMID 24675692, 2014). "While IFN provides short-term protection, IRF-1 is induced with delayed kinetics and controls viral replication at later stages of infection." (PMID 24675692, 2014). "Intranasal VSV infection of IRF-1+/−Mx2Luc induced reporter gene expression in the whole body, with a major response in the region of the liver 24 hours post infection." (PMID 24675692, 2014). "While all IRF-1+/−IFNARfl/flNesCre+/− mice died 6 days post infection, IRF-1 deficient IRF-1−/−IFNARfl/flNesCre+/− mice died between day 2 and 5 post infection." (PMID 24675692, 2014). "Viral titers were detectable in all brain parts of both, WT and IRF-1−/− mice 2 days post infection." (PMID 24675692, 2014). "While type I IFN plays a critical role in early stages of infection, IRF-1 is essential in limiting viral replication at later stages." (PMID 24675692, 2014).